ISG20L2 (interferon stimulated exonuclease gene 20 like 2)
Description:
3'-> 5'-exoribonuclease involved in ribosome biogenesis in the processing of the 12S pre-rRNA. Displays a strong specificity for a 3'-end containing a free hydroxyl group.
Synonyms: HSD38; FLJ12671
Tractability: PROTAC: its protein half-life has been measured.
Gene: Protein-coding gene on chromosome 1 (156,720,796 to 156,728,766, reverse strand). Ensembl gene ENSG00000143319.
Subcellular location: Nucleus, nucleolus
Subcellular location (Human Protein Atlas): Nucleoplasm
Pathways (Reactome):
Metabolism of RNA: Major pathway of rRNA processing in the nucleolus and cytosol
Gene Ontology:
Molecular function: protein binding; RNA binding; 3'-5'-RNA exonuclease activity; exonuclease activity; nucleic acid binding
Biological process: RNA processing
Cellular component: nucleolus
Genetic constraint (gnomAD): Loss-of-function variants: 14 observed, 29.3 expected, observed/expected ratio (o/e) 0.48, 90% interval 0.31 to 0.75. The upper end of that interval is the gene's LOEUF score, 0.75, which puts it in group 3 of 6, group 1 being the genes least tolerant of losing a copy. Missense variants: 393 observed, 457.91 expected, observed/expected ratio (o/e) 0.86, 90% interval 0.79 to 0.93. Synonymous variants: 157 observed, 175.9 expected, observed/expected ratio (o/e) 0.89, 90% interval 0.78 to 1.02.
Homologues: Orthologues: chimpanzee ISG20L2 (99% identical), macaque ISG20L2 (97% identical), pig ISG20L2 (86% identical), rabbit ISG20L2 (82% identical), guinea pig ISG20L2 (78% identical), rat Isg20l3 (77% identical), rat Isg20l1 (77% identical), mouse Isg20l2 (76% identical), rat Isg20l3 (74% identical), tropical clawed frog isg20l2 (48% identical), Drosophila melanogaster prage (25% identical), Caenorhabditis elegans pqe-1 (20% identical), and 1 more. Paralogues in human: AEN (36% identical), REXO4 (26% identical), ISG20 (24% identical), REXO1 (22% identical), REXO5 (18% identical).
Diseases named in the same sentence as ISG20L2 in open-access papers:
ISG20L2 is named in the same sentence as 8 diseases in open-access papers, as found by Europe PMC text mining. Sharing a sentence is not in itself a finding about the gene and the disease. The quoted sentences say what the papers report.
breast carcinoma (2 papers, 2021 to 2022). "Recently, several independent omics analyses identified ISG20L2 as a prognostic marker in different human cancers, including hepatocellular carcinoma, lung adenocarcinoma, and breast cancer." (PMID 36040812, 2022). "While the mean methylation levels of ISG20L2 significantly increased in breast cancer compared to normal breast tissues (P < 0.05)." (PMID 34341433, 2021). "In DiseaseMeth 2.0 database, the correlation analysis of DNA methylation patterns of hub genes with mRNA expression revealed that CENPL, MRPL3 and LSM4 were hypomethylated in breast cancer samples compared with adjacent normal ones, while ISG20L2 was hypermethylated in breast cancer sample." (PMID 34341433, 2021). "To further elucidate the lurking biological functions of CENPL, ISG20L2, MRPL3 and LSM4 in breast cancer occurrence and development, we conducted GSEA and GSVA using METABRIC dataset." (PMID 34341433, 2021). "Based on the TCGA_BRCA and match TCGA normal and GTEx data of GEPIA database, the mRNA expression levels of these genes (CENPL, ISG20L2, MRPL3 and LSM4) were also significantly higher in breast cancer tissues than normal tissues." (PMID 34341433, 2021). "The expression levels of each hub gene (CENPL, ISG20L2, MRPL3, and LSM4) was correlated with EZH2 in three different breast cancer cell lines (p < 0.01)." (PMID 34341433, 2021). "Considering the five hub genes, which were identified based on PPI networks and WGCNA, share the same signaling pathways during breast cancer progression, we conducted correlation analysis between the four novel hub genes (CENPL, ISG20L2, LSM4 and MRPL3) and EZH2." (PMID 34341433, 2021). "Additionally, genetic alterations of CENPL, ISG20L2, MRPL3, and LSM4 were further examined in cBioPortal database, showing these four hub genes were altered in 570 (26%) of 2173 breast cancer patients." (PMID 34341433, 2021). "Compared to normal mammary epithelial cell (MCF10A), the RCPs of each hub gene in both breast cancer cell lines (MCF7 and MDA-MB-231) showed a significant increase (p < 0.05), but the RCPs of ISG20L2 were reduced and the LSM4 were similar as observed in SKBR3 cell." (PMID 34341433, 2021). "Among these, many studies on EZH2 in breast cancer have been reported, but no studies are related to the roles of CENPL, ISG20L2, MRPL3 and LSM4 in breast cancer." (PMID 34341433, 2021). "As an oncogene, growing evidence has identified EZH2 was closely related to breast cancer development and progression through multiple molecular mechanisms, but no studies are related to the roles of CENPL, ISG20L2, MRPL3 and LSM4 in breast cancer." (PMID 34341433, 2021).
hepatocellular carcinoma (2 papers, 2021 to 2022). A malignant tumor that arises from hepatocytes. "As one of target genes regulated by miR-139-3p, ISG20L2 has recently been related to hepatocellular carcinoma prognosis, consistent with an immunogenomic landscape study which adds the roles of ISG20L2 in reflecting levels of infiltration in diverse immune cells." (PMID 34026765, 2021).
lymph node metastasis (1 paper, 2021). "In this study, our data not only showed the expression level of CENPL, ISG20L2, LSM4 and MRPL3 were strongly associated with age, lymph node metastasis and higher SBR grade, but also significantly upregulated in triple negative breast cancer patients compared to non-triple negative breast cancer." (PMID 34341433, 2021).
cancer (3 papers, 2021 to 2022). A tumor composed of atypical neoplastic, often pleomorphic cells that invade other tissues. "Therefore, the oncogenic role of ISG20L2 across cancers remains uncertain and requires further investigation." (PMID 36040812, 2022). "Additionally, high expression of ISG20L2 has been found in several cancers and affected cancer occurrence in a variety of aspects." (PMID 34026765, 2021).
tumor (2 papers, 2011 to 2021). "In the gene set developed by applyingthe BVS procedure on the normal tissue dataset, a high expression ofPPP2R4, PRELP, CALLA,ISG20L2 was predictive of tumour capsular penetration." (PMID 21479216, 2011).
ISG20L2 also shares sentences with these, for which no sentence is quoted: lung adenocarcinoma (2 papers); infection (1); triple-negative breast carcinoma (1).